CD1D (CD1d molecule)
Diseases named in the same sentence as CD1D in open-access papers (continued):
Sharing a sentence is not in itself a finding about the gene and the disease.
melanoma (22 papers, 2006 to 2025). A malignant, usually aggressive tumor composed of atypical, neoplastic melanocytes. "Intriguingly, when Ja18−/− mice bearing B16 melanoma tumors were treated with CpG, tumor growth was significantly reduced compared to CD1d−/− mice (deficient in type I and type II NKT cells)." (PMID 34680322, 2021). "This is an important component of the immunosurveillance in C57Bl/6 mice since CD1d-KO animals are significantly more susceptible to melanoma growth than WT mice." (PMID 19968878, 2009). "Moreover, our data suggest that the enhanced melanoma colonization seen in Mcpt4/Mcpt6/Cpa3-deficient animals is associated with a defective CXCL16/CD1d/iNKT cell axis." (PMID 28212574, 2017). "Therefore, we sought to evaluate whether B2M and CD1D gene expression is governed by epigenetic changes associated with DNA methylation in the tumor microenvironment of melanoma." (PMID 37077920, 2023). "Hence, the high melanoma burden of Mcpt4/Mcpt6/Cpa3-deficient animals is accompanied by low expression of CD1d, introducing the possibility that CD1d might have a role in regulating melanoma colonization of the lung." (PMID 28212574, 2017). "Co-expression and correlation profile of B2M with CD1D, CD1B, and FCGRT dissociates in melanoma patients following B2M expression loss." (PMID 37077920, 2023). "Evidence of the expression profile of β2M, CD1d, and CD1b in melanoma tissues can be found in the Human Protein Atlas collection." (PMID 37077920, 2023). "In agreement with this notion, the expression of the CD1d gene correlated negatively with the expression of melanoma-specific genes." (PMID 28212574, 2017). "Overall, these data demonstrate the important role of CTLs in the antitumor effects observed for this melanoma model after the combined CD1d-immunotherapy and OVA/CpG-ODN vaccine." (PMID 25426294, 2014). "In the present work, it is evident that type I NKT cells (invariant or iNKT) play an important role in the protection against B16F10-Nex2 melanoma cells based on the enhanced tumor progression in CD1d-KO animals." (PMID 19968878, 2009). "In a melanoma metastatic model, however, we found that iGb3 (20 μg/ml)-loaded CD11c+CD1d+ BMDCs reduced the number of lung nodules 4-fold, the same level of anti tumor protection obtained with α-GalCer at 200 ng/ml." (PMID 19968878, 2009). "CD1d-restricted iNKT cells are protective against murine melanoma B16F10-Nex2 growing subcutaneously in syngeneic C57Bl/6 mice as inferred from the fast tumor development in CD1d-KO in comparison with wild type animals." (PMID 19968878, 2009). "Notably, the expression of CD1D within the melanoma TIME influenced the infiltration of various immune cell types, particularly memory B cells, M0 macrophages, CD8+ T cells, and others." (PMID 38279987, 2024). "However, their cytotoxic activity against both unloaded and αGC-loaded THP-1 CD1d cells was significantly reduced when co-cultured with melanoma cells." (PMID 37444608, 2023). "In addition, histologically similar tumors to anaplastic carcinoma like sarcoma and malignant melanoma revealed distinct CD1d staining patterns." (PMID 31560833, 2019). "The correlation between reduced CD1d expression and enhanced tumor progression has been reported in a variety of types of CD1d-transduced solid cancers, including breast, cervical, ovarian, prostate, lung, and melanoma." (PMID 29326711, 2017). "CD1d immunohistochemistry was performed in samples of 18 anaplastic, 17 follicular, 27 papillary, and 4 medullary thyroid carcinomas as well as in 19 specimens from normal thyroid tissue and additionally in 10 samples of sarcoma, seven malignant melanoma and three spindle‐cell lung carcinoma." (PMID 31560833, 2019). "Interestingly, CD1d-dependent cross-presentation by DC of GD3 derived from human melanoma cells was shown to activate cytokine responses in iNKT cells, suggesting mechanisms whereby CD1d-negative tumors may influence the antitumor immune response." (PMID 23118781, 2012).
melanoma (continued). "When iNKT cells were co-cultured with melanoma cell lines and stimulated with αGC-loaded THP-1 CD1d cells, the production of IFN-γ was significantly (p ≤ 0.05) reduced at both E:T ratios tested." (PMID 37444608, 2023). "Methylation reactions in the TME of melanoma impact the expression of B2M and SPI1, which controls CD1D expression." (PMID 37077920, 2023). "In specimens with melanoma tumors, NK cells (CD16 + CD56+) and iNKT cells (CD1D + TCRvB8.1) from peripheral blood are active (CD107a+) and preserve immature markers, such as Sca-1+, in addition to the transcription factor/immaturity c-kit (CD117+)." (PMID 37895943, 2023). "Based on the FAM molecular subtypes, we identified the 6 FAMGs (ACSL5, ALOX5AP, CD1D, CD74, IL4I1, TBXAS1) that play vital regulatory roles in the melanoma TME." (PMID 36466837, 2022). "In a B16 melanoma model expressing HER2, treatment with a CD1d-antibody fusion protein targeting HER2 increased iNKT cell inflammatory cytokine production and targeted lysis of tumor cells, decreasing metastasis formation." (PMID 34680322, 2021). "Together, these findings indicate a protective role of mast cell-specific proteases in melanoma dissemination, and suggest that this effect involves a CXCL16/CD1d/NKT cell axis." (PMID 28212574, 2017). "To evaluate whether the expression of CD1D, CD1B, and FCGRT is affected in a β2M-dependent manner in malignant melanoma, we first obtained the expression levels of all β2M-STRING-predicted interacting genes (n = 20) from the GDC-TCGA-SKCM study." (PMID 37077920, 2023). "As opposed to the cell membrane region, β2M, CD1d, and CD1b were mostly expressed in the cytosol of malignant melanoma tissues." (PMID 37077920, 2023). "However, when co-cultured with melanoma cells at a 1:2 ratio, iNKT cells demonstrated a diminished ability to be triggered by both αGC-unloaded and αGC-loaded THP-1 CD1d cells." (PMID 37444608, 2023). "This notion was supported by our observed negative correlation between CD1d expression and melanoma burden." (PMID 28212574, 2017). "Another report, which substantiates these findings, demonstrated that treating human and murine lung cancer and melanoma cell lines with HDAC2 inhibitors induce CD1d expression, although the functional relevance was not investigated." (PMID 29326711, 2017). "Moreover, in vivo HSC-iNKT cells could also protect against a multiple myeloma or a melanoma that expressed CD1d, without the requirement of α-GalCer, by the recognition of tumor-endogenous lipid antigens." (PMID 35615083, 2022). "We provide further evidence that epigenetic changes in the TME of melanoma tumors have a direct impact on B2M and an indirect impact on CD1D gene expression (through SPI1) but not on CD1B and FCGRT expression in melanoma patients from the TCGA dataset." (PMID 37077920, 2023). "To determine whether the reduced degranulation of iNKT cells affected cytokine production, we stimulated iNKT cells with αGC-unloaded/loaded THP-1 CD1d cells and analyzed the supernatant for secreted IFN-γ and IL-4 levels after 4 days of culture, in the presence/absence of melanoma cells." (PMID 37444608, 2023).
autoimmune disease (16 papers, 2008 to 2024). A disorder resulting from loss of function or tissue destruction of an organ or multiple organs, arising from humoral or cellular immune responses of the individual to their own tissue constituents. "Celiac disease (C), also considered an autoimmune disease, includes an increased percentage of CD24hiCD38hi Bregs, as well as increased expression of CD1d on IL-10 secreting B cells under chronic intestinal inflammatory conditions." (PMID 38134245, 2024). "Given the broad cellular expression of CD1d, the metabolic function described here will have wide implications for immune regulation in homoeostasis as well as in metabolic, infectious and autoimmune diseases." (PMID 36344546, 2022). "Also, clear evidence for immune response to phospholipids via CD1b and CD1d invites consideration of possible B cell–T-cell interactions in the anti-phospholipid antibody syndrome, an autoimmune state associated with systemic lupus erythematosus and other autoimmune diseases." (PMID 30610190, 2019). "However, in autoimmune diseases, studies have found that the expression of CD1d on B cells in individuals with SLE patients is defective." (PMID 32973780, 2020). "Adaptive stimulation of dNKT cells may occur in situations such as in autoimmune disease where self‐lipid agonist ligands may be presented on CD1d and result in the regulation of immunity by dNKT cells through the production of regulatory/TH2 cytokines." (PMID 30427069, 2019). "Therefore, our designed Th2- and Th17-biasing ligands could be used to regulate autoimmune disorders through the CD1d-NKT cell axis." (PMID 32978421, 2020). "Thus, some CD1d-reactive T-cells might protect against autoimmunity, whereas others might enhance autoimmune disease." (PMID 23531237, 2013). "Bregs expressing CD1d and CD5 suppress proliferation and differentiation of Th1/Th17 immune responses, and defects in CD1dhiCD5+ Bregs can exacerbate disease symptoms of autoimmune diseases in murine models." (PMID 38134245, 2024). "A vast amount of literature supports a central role for CD1d/NKT cells in a variety of disease contexts, including inflammatory, infectious or autoimmune diseases." (PMID 38579449, 2024). "As CD5/CD1d are regulatory facrors in mouse models of inflammation and CD24/CD38 are involved in human autoimmune diseases, we assessed the expression of these markers in CD19+ B cells via flow cytometry." (PMID 26378021, 2015).
lupus (16 papers, 2008 to 2025). "Thus, β2m-deficiency may affect lupus via at least three possible mechanisms: 1) the effects of FcRn on IgG catabolism; 2) the immunoregulatory role of CD1d, and 3) the ability of CD1d to bind phospholipids to induce anti-phospholipid autoimmunity." (PMID 23531237, 2013). "The importance of CD1d expression in the regulatory function of B cells has been demonstrated in the context of chronic intestinal inflammatory disease and systemic lupus erythematosus." (PMID 38134245, 2024). "We demonstrated with flow cytometry (FACS) immunophenotyping that after pCons treatment the CD19+CD1d+ regulatory B cell subset was significantly increased in BWF1 lupus mice compared to naïve mice." (PMID 34093553, 2021). "In this model, CD1d-dependent T cells were depleted in order to investigate the role of these cells in genetically lupus-prone NZB/NZW F1 (BWF1) mice, by injections of 50 million irradiated CD1d-transfected A20 cells." (PMID 32085540, 2020). "In humans, CD1d expression on B cells and iNKT cell frequency and proliferative capacity generally decreases in lupus patients, suggesting a protective role for iNKT cell during lupus." (PMID 30061888, 2018). "One study showed that CD1d-reactive iNKT cells contribute to the development of lupus in BWF1 mice by promoting autoantibody production by B cells." (PMID 22761630, 2012). "Furthermore, similar data were obtained in more than one knockout strain, namely β2m° and CD1d° BWF1, arguing against the possibility that other lupus-susceptibility genes are responsible for our observations." (PMID 23531237, 2013). "Ample evidence suggests a regulatory role of CD1d-restricted T-cells in lupus and related diseases." (PMID 23531237, 2013). "CD1d-restricted invariant natural killer T cells (iNKT cells) may play an important role in the pathogenesis of systemic lupus erythematosus (SLE)." (PMID 34936686, 2021). "Treatment with IL-35 significantly increased the numbers of IL-10-secreting CD1d+CD5+ Bregs and ameliorated renal damages in lupus-prone MRL/Lpr mice." (PMID 31795353, 2019). "Use of a blocking anti-CD1d monoclonal antibody to treat BWF1 mice augmented the Th2 responses and ameliorated lupus." (PMID 22761630, 2012). "Dex drug and W treatment did not affect Tregs (CD4+ CD25+ FOXP3+) and Bregs (CD5+ CD1d+) in lupus mice." (PMID 40158179, 2025). "Furthermore, when the spleen cells from lupus mice (MRL/lpr mice) were cultured with PD-L1 positive MDSCs, only PD-L1 positive MDSCs form control mice remarkably suppressed plasma cell (CD19-CD138+) population and expanded IL-10 producing B 10 cell (CD19+CD5+CD1d+)." (PMID 33986739, 2021).
asthma (15 papers, 2011 to 2024). "Other examples of potential therapeutic applications for neutralizing NKT cells with anti-CD1d antibodies includes asthma and eosinophilic esophagitis." (PMID 38622654, 2024). "For example, house dust extracts and the fungus (Aspergillus fumigatus)-derived glycosphingolipid, asperamide B, directly activate iNKT cells in a CD1d-dependent manner, ultimately resulting in asthma exacerbation." (PMID 34829848, 2021). "In addition, we further assessed Breg cells (CD19+CD1d+CD5+) as a negative regulator of immunity in asthma and SCIT groups." (PMID 34804031, 2021). "Invariant natural killer T (iNKT) cells, which are activated by T cell receptor (TCR)-dependent recognition of lipid-based antigens presented by the CD1d molecule, have been shown to participate in the pathogenesis of many diseases, including asthma and liver injury." (PMID 31850305, 2019). "A variety of studies suggested that CD1d-restricted NKT cells could be critical inducers of asthma in murine models." (PMID 30319649, 2018). "CD4+ NKT cells may also have a critical role in the pathogenesis of asthma and produce IL-5 when co-cultured with CD1d+ antigen presenting cells and IL-2." (PMID 21423619, 2011). "Also, β2m-deficient mice, which are unable to express CD1d molecules, develop asthma despite lacking iNKT cells." (PMID 30319649, 2018). "The presence of CD1d in mice greatly facilitated research on NKT cells, which has shown that these cells play pivotal roles in development of asthma, pulmonary infection, fibrosis, and other pulmonary disorders." (PMID 30319649, 2018). "In this report, however, CD1d-restricted iNKT cells accounted for 2–7% of total CD3+ cells in the BALF of asthmatic patients, and only 1 patient with severe asthma had an iNKT cell proportion of 64.5%." (PMID 30210497, 2018). "The Th2 inflammatory response and severity of asthma were both reduced in CD1d−/− mice, which lack iNKT cells due to absence of the non-classical class I restricting element for iNKT cells, when sensitized and challenged with OVA." (PMID 33800208, 2021). "An ovalbumin (OVA)-induced model of asthma first showed that mice lacking iNKT cells (i.e., CD1d- or Vα14-Jα18-deficient mice) do not develop AHR, which is a critical feature of asthma." (PMID 30319649, 2018). "Adoptive transfer of a cell population enriched for cells that bound PBS-57-loaded CD1d tetramer and TCR-β, i.e., iNKT cells (>76% tetramer and TCR-β double-positive), significantly enhanced Th2 inflammatory responses in the OVA-induced asthma model." (PMID 25830340, 2015). "To determine the specific role of iNKT cells in the development of Th2 inflammatory responses in asthma, we examined the Th2 inflammatory response in CD1d-/- mice, which lack the iNKT cells due to the absence of the class I restricting element of iNKT cells." (PMID 25830340, 2015). "Moreover, as shown by β2m-knockout mice, noninvariant NKT cells that recognize β2m-independent CD1d also participate in the development of AHR in ovalbumin-induced asthma mouse models; treatment of these mice with anti-CD1d decreased AHR57." (PMID 37696897, 2023). "In the ovalbumin asthma model, CD1d−/− mice do not develop airway hyper-responsiveness." (PMID 21853044, 2011). "A possible reason to explain the discrepancies between studies concerning the implication of iNKT cells in asthma severity is that, in addition to iNKT cells, type II NKT cells were also absent in β2m−/− and CD1d−/− mice, while β2m−/− mice also lack CD8 T cells." (PMID 30105031, 2018).
Autoimmunity (14 papers, 2008 to 2024). The occurrence of an immune reaction against the organism's own cells or tissues. "Since β2m promotes the activation of CD8+ and NKT cells via its association with MHC class I and CD1d, respectively, β2m deficiency may aggravate aspects of autoimmunity that are normally controlled by such potentially regulatory T-cells." (PMID 23531237, 2013). "Indeed, CD1d-deficient mice were largely protected against manifestations of autoimmunity including humoral and cellular responses." (PMID 18474357, 2008). "B cells expressing CD1d are partly involved in autoimmunity regulation as a checkpoint for B cell activation with subsequent auto-antibody production and contributions to disease progression." (PMID 38134245, 2024). "Invariant natural killer T (iNKT) cells, a subset of unconventional T cells that recognize glycolipid antigens in a CD1d-dependent manner, are crucial in regulating diverse immune responses such as autoimmunity." (PMID 38274786, 2023). "This demonstrates that the regulatory role of iNKT on autoimmunity strongly correlates with CD1d expression on B-cells, and CD1d is upregulated in autoreactive B-cells." (PMID 31683641, 2019). "iNKT cells are a distinctive subtype of CD1d-restricted T cells, which recognize glycolipid antigens presented by the CD1d molecule, involved in regulating autoimmunity and capable of producing various Th1, Th2, and Th17 cytokines." (PMID 23133752, 2012). "CD1d-restricted immunity can therefore lead to either immunosuppression or autoimmunity depending upon the type of innate effector dominating during the infection." (PMID 21255407, 2011). "Additionally, these LiNKTR1 cells suppress autoantigen presentation, and recognize CD1d expressed on conventional B cells to induce IL-10+IL-35-producing regulatory B (Breg) cells, leading to the suppression of liver and pancreas autoimmunity." (PMID 35672409, 2022). "However, the inability of αGalCer/CD1d-NPs to blunt liver-distal autoimmunity (EAE) or normal immune responses (LM infection in both liver and spleen, as well as antibody responses to a nominal antigen vaccine), argues against this scenario." (PMID 35672409, 2022). "β2-microglobulin (β2m) is required for the surface expression of MHC class I and class I-like proteins such as CD1d, Qa1 and neonatal Fc receptor (FcRn), all of which may impact the development of autoimmunity." (PMID 23531237, 2013). "Cytokine-mediated and CD1d-dependent interactions between iNKT cells and myeloid and lymphoid cells enable iNKT cells to contribute to the activation of multiple cell types, with important impacts on host immunity to infection and tumors and on the prevention of autoimmunity." (PMID 29967611, 2018). "Aside from CD1d, the study of group 1 CD1-restricted T cells under conditions of dyslipidemia and autoimmunity remains obscure." (PMID 30061888, 2018). "In a previous study, adoptive transfer of CD1d-reactive single positive T-cells induced a lupus-like disease in nude mice, whereas CD1d-reactive TCRαβ+CD4-CD8- T-cells prevented the induction of autoimmunity." (PMID 23531237, 2013). "In Novosphingobium aromaticivorans infection in mice, CD1d presentation of alpha-glycuronosylceramide from the bacterial cell wall activates NKT cells and ultimately results in liver-specific autoimmunity." (PMID 21255407, 2011). "We report a novel dichotomous role of β2m and CD1d, whereby these molecules differently regulate autoimmunity against phospholipid versus non-phospholipid autoantigens." (PMID 23531237, 2013). "However, since type II NKT cells are harder to identify in human samples due to a lack of specific surface markers like α- GalCer/CD1d tetramers, they are much less studied than iNKT cells, and their roles in autoimmunity remain to be further validated." (PMID 35619713, 2022).